EGFR (epidermal growth factor receptor)
Diseases named in the same sentence as EGFR in open-access papers (continued):
Sharing a sentence is not in itself a finding about the gene and the disease.
tumor (continued). "Adjuvant Osimertinib and Atezolizumab has also been incorporated into the recent guidelines in EGFR mutant and ≥1% Programmed Cell Death Ligand-1 (PDL1) expressing tumours respectively." (PMID 40486071, 2025). "The ErbB receptor family (EGFR, HER2, ErbB3, ErbB4) is expressed in lactotroph cells, promoting prolactin secretion, and inhibiting these receptors can lead to tumor regression." (PMID 41013821, 2025). "In this context, miRNAs inhibiting expression of PTEN (miR-425 and miR-148a) should be considered as oncomirs, and those inhibiting KRAS, EGFR, PIK3CA, TGFBR1, and SMAD2 (let-7g, miR-150, miR-128, miR-139, miR-148a, miR-148b) as tumor suppressors." (PMID 40868120, 2025). "Here we reveal that EGFR governs tumorigenic agrin expression and then sensitizes the RTK to tumor‐stiffness through integrin mechanosignaling." (PMID 40165020, 2025). "Preclinical studies have shown that EGFR signaling exerts an immunomodulatory role by regulating MHC I/II and PD-L1 expression on tumor cells and lymphocyte activity." (PMID 40831747, 2025). "This upregulation promotes tumor growth and survival, making the EGF/EGFR axis a potential therapeutic target." (PMID 40677703, 2025). "Its interactions with binding proteins—such as CD44, EGFR, integrins, CD280, and CD176—and its dual role in both tumor and stromal compartments highlight a unique therapeutic vulnerability that extends beyond conventional single-pathway targeting strategies." (PMID 41479915, 2025). "In preclinical models, combination therapy has been shown to suppress both EGFR- and RET-driven signaling, resulting in enhanced tumor regression compared to monotherapy." (PMID 40416863, 2025). "This hypothesis was confirmed using EGFR FISH, which revealed EGFR amplification (based on the definition of Colorado Scoring Criteria) in all cases with a low IC Ct value, including three with large EGFR gene clusters and one with at least 15 copies of the EGFR signals in ≥10% of tumor cells." (PMID 40310364, 2025). "Mertk has been reported to activate multiple signaling pathways (JAK/STAT, MAPK, PI3K/AKT, EMT, and PD-1/PD-L1) to promote tumor cell migration, immune escape, and cancer stem cell (CSC) transformation, and act as bypass mechanisms to EGFR blockade." (PMID 39996058, 2025). "By conjugating an EGFR-degrading PROTAC to folic acid–polyethylene glycol (FA-PEG) via a GSH-responsive disulfide bond, MPRO exploits folate receptor overexpression on tumor cells for selective internalization." (PMID 40284496, 2025). "The ERBB2 gene is a member of the epidermal growth factor receptor (HER) family and is related to a variety of cell signaling pathways that play important roles in cell proliferation, tumor formation, and apoptosis." (PMID 40842594, 2025). "The upregulation of epoxyeicosatrienoic acids (EETs), products of this pathway, activates the EGFR and PI3K/AKT/MAPK signaling pathways, promoting tumor formation and metastasis." (PMID 40076494, 2025). "No gender-related prognostic heterogeneity was observed in other subgroups, including age, tumor location, T stage, pathological type, bone/lung/liver metastasis, chemotherapy, radiotherapy, AAT therapy, EGFR-TKI treatment, or ICIs treatment (P > 0.05)." (PMID 41272627, 2025). "By downregulating EGFR in NSCLC, miR-143–3p, on the other hand, acts as a tumor suppressor and has been shown to prevent cell proliferation and invasive potential." (PMID 41080754, 2025). "The identification of clonal subpopulations that express different RTKs (EGFR, PDGFRA, and MET) in a mutually exclusive manner fuelled interest into characterising intra-tumour heterogeneity in GBM." (PMID 39816516, 2025).
tumor (continued). "For instance, anti-EGFR and anti-VEGF monoclonal antibodies disrupt oncogenic signaling and tumor angiogenesis, respectively, and have demonstrated substantial clinical efficacy in selected patient populations." (PMID 41361128, 2025). "The aberrant activation of EGFR primarily triggers the MAPK, PI3K/AKT, and JAK/STAT pathways, which collectively enhance tumor cell proliferation and inhibit apoptosis." (PMID 40427514, 2025). "Compared with conventional anti-EGFR monoclonal antibodies (such as cetuximab), EGFR/CD3 bispecific antibodies not only block EGFR-mediated tumor proliferation signaling but also actively recruit T cells to exert cytotoxic effects." (PMID 41333481, 2025). "CAFs are a significant component of the CRC tumor stroma and secrete ECM proteins like collagen and other factors that promote resistance to various treatments, including chemotherapy, anti-EGFR therapy, and immunotherapy." (PMID 40076613, 2025). "This pro-inflammatory environment facilitates the expansion of pre-existing oncogenic clones and reprograms EGFR -mutant alveolar type II (AT2) epithelial cells into a progenitor cell state, fostering tumour initiation and progression." (PMID 41274118, 2025). "Research indicates that EGFR overexpression occurs in more than half of HCC patients, correlating significantly with tumor metastasis, poor survival rates, and high invasiveness." (PMID 40699663, 2025). "These consistent findings of FAK upregulation in EGFR-TKI-resistant cells and tumor tissues not only underscore its role in mediating chemoresistance but also position it as a promising therapeutic target." (PMID 41281943, 2025). "Another study developed a nanoparticle‐based system that successfully targeted EGFR‐TKI, reducing tumor volume and enhancing treatment efficacy." (PMID 40682256, 2025). "GE11 peptide has a high affinity for epidermal growth factor receptor (EGFR), enabling tumor targeting." (PMID 40385535, 2025). "A 53-year-old man with a right submandibular mass underwent primary tumor resection with ipsilateral radical neck dissection and was diagnosed with SDC along with high EGFR and HER2 expression." (PMID 40486390, 2025). "Most reports describe FGFR3::TACC3 as an acquired event after EGFR-TKI therapy, and its presence in a TKI-naïve tumor suggests a potential de novo co-activation of independent oncogenic pathways." (PMID 41301039, 2025). "For instance, EZH2’s dual role in suppressing tumor suppressor genes (e.g., CDKN1A, NLRP3) while activating pro-survival signals (e.g., Snail/EGFR) highlights its adaptability as a molecular switch in resistance trajectories." (PMID 40701777, 2025). "Concurrently, inhibition of YTHDF1 and YTHDF3 in BC cells decreased tumor progression and metastatic capacity by metabolic impairment, reducing PKM2 activity and EGFR modulation accordingly." (PMID 41157107, 2025). "Another new bispecific EGFR/CD16A bispecific antibody, AFM24, kills tumor cells directly by activating NK cells and macrophages." (PMID 41179878, 2025). "This included for example for bendamustine EIF3M involved in cell proliferation, cell cycle progression and cell death, SMAD3 involved in epithelial-to-mesenchymal transition, tumor suppressor and metastasis formation, and UBXN1 influencing EGFR signaling." (PMID 41146244, 2025). "Despite these insights, the regulatory mechanisms governing EGFR splicing in LUAD remain poorly understood and necessitate further investigation to elucidate their impact on tumor biology and therapeutic outcomes." (PMID 40282505, 2025).
tumor (continued). "The stronger effect on EGF-induced phosphorylation resulted from blockade of ligand binding and receptor dimerization by the dual epitope EGFR arm as anticipated, while the avidity effect maintained a strong HGF blockade in the tumor cells." (PMID 40452841, 2025). "These cells often exhibit enhanced signaling through pathways such as EGFR or PDGFRA, which are critical for driving tumor growth." (PMID 40255400, 2025). "We excluded the interference of other cells in tumor tissues at the single-cell level and found that patients who responded to ICI treatment had lower EGFR scores." (PMID 40574864, 2025). "Together, EGFR and TLR signaling foster a tumor-promoting environment, positioning them as valuable targets for therapeutic intervention in CRC." (PMID 41419456, 2025). "REGN7075 is a first-in-class EGFR x CD28 BsAb that activates T cell response by bridging CD28-expressing T cells and EGFR-expressing tumor cells." (PMID 40565299, 2025). "Tumor xenograft assays demonstrated resistance to EGFR-TKI-afatinib in the shSMARCB1 group, with a notable increase in tumor size upon SMARCB1 silencing." (PMID 39971779, 2025). "Enhanced phosphorylation of EGFR, PI3K, and AKT were displayed in STARD4 overexpression tumor tissues." (PMID 40831538, 2025). "For example, an EGFR inhibitor plus a BCAT1 inhibitor tackled two separate resistance mechanisms in lung cancer models and achieved deeper tumor regressions than either alone." (PMID 41502503, 2025). "LASSBio-1971 inhibits different forms of EGFR, has a good membrane permeability that mimics the blood–brain barrier (BBB), and already displayed promising results in various tumor cell lines." (PMID 40650170, 2025). "Mitoxantrone effectively decreased the levels of both EGFR and TRAF6 in CRC cell lines, leading to significant reductions in cell proliferation and tumor spheroid formation." (PMID 41419456, 2025). "Amivantamab is a bispecific monoclonal antibody that binds to both EGFR and the c-MET receptor proteins on the cell surface, thereby blocking downstream signal transmission and inhibiting the proliferation of tumor cells expressing these proteins." (PMID 41239252, 2025). "In some designs, natural adenoviral receptors are ablated and replaced with tumor-specific ligands, such as antibodies targeting human epidermal growth factor receptor 2 (HER2) or peptides recognizing EGFR." (PMID 41228258, 2025). "Clinical analysis indicated that high level of tumor α5-nAChR is correlated with poor survival rates of LUAD patients, particularly in those expressing wild-type EGFR." (PMID 40143965, 2025). "In contrast, BL-B01D1, a novel BsADC targeting EGFR and HER3, has shown promising anti-tumor efficacy in clinical trials and utilizes the 2:2 format." (PMID 40057807, 2025). "The EGFR gene is part of the human epidermal growth factor (HER) family and plays a significant role in tumor development and progression." (PMID 40507907, 2025). "Beyond our work with the CDX model, we also evaluated the inhibitory effects of the nanobody on tumor growth using PDX models representing a patient that had developed resistance to both 2nd and 3rd generation EGFR‐TKI agents." (PMID 40521789, 2025). "Near infrared fluorophores IRDye 800 CW (emits at 805 nm) conjugated to large molecules, such as antibodies to EGFR and VEGF receptors, have slower kinetics of incorporation into tumor cells, which requires taking the drug 1–5 days before surgery." (PMID 41094345, 2025). "Comparable to EGFR, an even more profound 20-fold increase of AREG mRNA (left) and 30-fold increase of AREG protein levels was observed in MKN-74 tumor xenograft tissue slice cultures (right)." (PMID 39864337, 2025).
tumor (continued). "FMD intervention disrupts this pathogenic cycle through dual mechanisms - directly impairing tumor cell CCL2 production and indirectly modulating TAMs effector functions - thereby resensitizing malignancies to EGFR-targeted therapy." (PMID 40808689, 2025). "Blocking of EGFR signaling by inhibitors like cetuximab activates the PI3K/Akt/mTOR pathway, which is regulated by PTEN (Phosphatase and tensin homolog), a tumor suppressor gene." (PMID 40560045, 2025). "On the other hand, in tumours like the MDA-MB-231 cell line, which exhibits high EGFR and low EpCAM expression, targeting EGFR for NIR-PIT would be more effective." (PMID 40792441, 2025). "In NSCLC, drugs such as gefitinib and erlotinib target the epidermal growth factor receptor (EGFR) pathway, which is frequently altered in solid tumors, leading to enhanced tumor sensitivity and reduced aggressiveness." (PMID 40732249, 2025). "In breast cancer, nuclear-localized USP43 binds to the NuRD complex and exerts tumor-suppressive effects by deubiquitinating H2BK120 and suppressing the transcription of EGFR, whereas cytoplasmic retention of USP43 contributes to tumor progression." (PMID 40890129, 2025). "At the same time, the expression level of EGFR is negatively correlated with the infiltration of CD8+T cells in tumor tissue and TAP1, which is a transporter to represent tumor antigen in the MHC-I complex." (PMID 39820491, 2025). "The tumor-suppressive effects of 5-HT7R likely involve modulation of cAMP pathways, metabolic changes, and interference with EGFR signaling." (PMID 40565099, 2025). "The EGFR pathway has been identified as a main regulator of ALDH1A3 in LA, promoting tumor aggressiveness and resistance to gemcitabine." (PMID 40489465, 2025). "Last, targeting KAT7 with a specific inhibitor or HELDR with ASOs enhances anti-GBM activity of the EGFR inhibitor, Erlotinib, in orthotopic GBM tumor xenograft models." (PMID 40678238, 2025). "Taken together, the coordination of TGIF2/SOX2 promotes subcutaneous tumor size and liver metastasis by activating EMT and EGFR/MAPK signaling." (PMID 39781447, 2025). "Cetuximab, a chimeric anti-EGFR IgG1 approved by the FDA for HNSCC treatment, binds to EGFR, blocks its signaling pathways, and induces immune-mediated tumor cell death." (PMID 41211421, 2025). "These fragments then bind to the epidermal growth factor receptor (EGFR), activating its downstream Raf/ERK/AKT signaling pathway, inducing F-actin cytoskeleton reorganization, and enhancing tumor cell migration and VM formation ability." (PMID 41019994, 2025). "Arecoline increased collagen contraction, ROS accumulation, and the activation of tumor-promoting pathways, including TGF-β/Smad, EGFR, MAPK, and ferroptosis." (PMID 41439141, 2025). "Secreted GRP78 interacts directly with epidermal growth factor receptor (EGFR), activating the EGFR/SRC/STAT3 signaling pathway, which promotes tumor cell proliferation and counteracts sorafenib-induced apoptosis." (PMID 40002794, 2025). "Lapatinib is a 4-anilinoquinazoline kinase inhibitor of the intracellular tyrosine kinase domains of both epidermal growth factor receptor (EGFR [ErbB1]) and of HER2 [ErbB2], which inhibits ErbB-driven tumor cell growth." (PMID 40136358, 2025). "IQGAP1 mediates the activation of multiple signaling pathways, including EGFR and CXCR4, which are crucial for tumor cell behavior." (PMID 41035668, 2025). "According to the current study, NAT10 plays a crucial role in tumor resistance since its expression was much higher in EGFR-TKI-resistant NSCLC tissues and cells and increased resistance to EGFR-TKIs." (PMID 41310903, 2025). "Activated EGFR can upregulate VEGF expression, which can subsequently function as a bypass signaling pathway to sustain tumor growth and mediate resistance to TKI therapy." (PMID 41158851, 2025).
tumor (continued). "Given the low-EGFR and high-PD-L1 expression profiles of the RKO cell line, we generated a novel PD-L1 × HYAL AbEn using the cFAE technology to improve tumor specificity." (PMID 41228205, 2025). "The reverse transcription real-time PCR assay revealed higher expression of tumor markers CDKN2A, EGFR, and PDGFRL in monophasic SS." (PMID 41155410, 2025). "Early tumor shrinkage and depth of response serve as valuable prognostic markers in RAS wild-type metastatic CRC, particularly for patients treated with anti-EGFR antibodies." (PMID 40280867, 2025). "The aim of the current study was to demonstrate how TAVO412, a trispecific antibody targeting EGFR, cMET, and VEGF, controlled dysfunctional NSCLC tumor growth activities." (PMID 40452841, 2025). "The combination of EGFR-CAR-NK-92 cells and HSV-1 in vitro led to rapid lysis of BC cells and, in vivo, reduced tumor growth and extended survival to 80 days in a mouse model." (PMID 40281554, 2025). "The findings suggest that the EGFR mutant LUAD TME shows impaired DC maturation, reduced CD8+ T cell numbers, and decreased tumor cell elimination ability." (PMID 40130724, 2025). "VEGF upregulation in EGFR-mutant NSCLC cells contributes to TKI resistance, promoting angiogenesis and tumor progression." (PMID 40002883, 2025). "At the early stage of EGFR-TKI usage, we observed a short-term inhibition of tumor cell growth, an increased presence of CD8+ T cells, DCs and M1-like TAMs, along with impeding Treg infiltration and M2 polarization." (PMID 40510028, 2025). "We further demonstrate that elevated expression of ZFX/UGCG alters ganglioside levels and activates epidermal growth factor receptor (EGFR)-mediated PI3K/AKT/mTOR/MAPK signaling, leading to tumor progression." (PMID 40934285, 2025). "During treatment response, various EGFR-TKIs, including afatinib, erlotinib, and gefitinib, have been shown to enhance MHC class I and II expression on tumor cells, facilitating CD8+ T cell recognition and cytotoxicity." (PMID 40058234, 2025). "In lung cancer cells, inhibition of SCD activity by CVT-11127 impairs phosphorylation of EGFR, resulting in inactivation of downstream targets Akt and ERK, effectively controlling metabolism, proliferation, and survival of tumor cells." (PMID 41421797, 2025). "Patients who developed spinal metastases were significantly more likely to have an EGFR mutation in the primary tumor compared to those who did not develop spinal metastases, which could be explained by increased survival in the EGFR mutated tumors due to targeted therapies." (PMID 40647516, 2025). "Beyond cell-autonomous resistance, CAFs, as key components of the tumor microenvironment (TME), have been discovered to mediate resistance to anti-EGFR therapy in a context-dependent manner through increasing EGF and IGF-binding protein secretion." (PMID 40362183, 2025). "Elevated expression of proteins and phosphoproteins of downstream of EGFR/ERBB in cluster #3 and #1 suggests EGFR/ERBB, SRC, c-RAF/MAPK, and PI3K/AKT/mTOR/RICTOR signaling as a major tumor-promoting circuits of these cancers." (PMID 40011822, 2025). "A hyperplasia–dysplasia–neoplasia model of FDC proliferation has been proposed as the link between UCD-HV and FDCS and was thought to be supported by the EGFR overexpression in dysplastic FDC." (PMID 40646240, 2025). "EGFR overexpression is observed in 68% of HCC cases and correlates with metastasis, poor patient survival, and aggressive tumor characteristics." (PMID 40699663, 2025). "Despite the availability of EGFR tyrosine kinase inhibitors (TKIs), clinical trials have shown limited success due to the malignant adaptive resistance mechanisms employed by GBM tumor cells." (PMID 39859381, 2025). "The percentage of tumor cells positive for target protein expression and staining intensity of DARPPC, DARPPN, and EGFR were quantified using a modified immunohistochemical scoring scheme." (PMID 40969344, 2025).